TRPV1 (transient receptor potential cation channel subfamily V member 1)
Diseases named in the same sentence as TRPV1 in open-access papers (continued):
Sharing a sentence is not in itself a finding about the gene and the disease.
cancer (continued). "Moreover, TRPV1 expression levels were markedly lower in late-stage (stage III-IV) than in early-stage (stage I-II) tumors in pan-cancer (p = 2.80 × 10−28)." (PMID 36304985, 2022). "The role of TRPV1 in cancer is dependent on the cancer type." (PMID 35806388, 2022). "Capsaicin induced TRPV1-dependent apoptosis in some cancers, such as prostate." (PMID 35477804, 2022). "Our analysis revealed that TRPV1 expression had a marked positive correlation with tumor purity in pan-cancer and seven cancer types (p < 0.01), while it showed a significant negative correlation with stromal content in pan-cancer and nine cancer types (p < 0.05)." (PMID 36304985, 2022). "TRPV1 upregulation correlates with decreased tumor proliferation, tumor driver gene expression, genomic instability, and tumor immunosuppressive signals in various cancers." (PMID 36304985, 2022). "Next, we sought to determine cancer-induced changes in neuronal TRPV1 function." (PMID 35260737, 2022). "A better understanding of TRPV1 sensitization in the setting of cancer could provide insight into how TRPV1-mediated cancer nociception could be alleviated or preempted." (PMID 35260737, 2022). "Furthermore, we compared TRPV1 expression levels among subtypes of several common cancer types, including BLCA, BRCA, and LGG." (PMID 36304985, 2022). "Likewise, TRPV1 expression levels also displayed a significant inverse correlation with cell cycle scores in pan-cancer (p = 9.75 × 10−71; ρ = −0.24) and in six cancer types (p < 0.01)." (PMID 36304985, 2022). "TRPC4, TRPV2, TRPV1, and TRPV3 loss variations were found in nearly all cancers." (PMID 35831825, 2022). "Different phytocannabinoid signalling occurs via TRPV1, a non-selective Ca2+-permeable channel transporter that is central to a plethora of cancer-associated processes." (PMID 36497400, 2022). "However, TRPV1 expression levels had a positive correlation with the ratios of immunostimulatory over immunosuppressive signatures (CD8+ T cell/PD-L1) in pan-cancer and in five cancer types (p < 0.05)." (PMID 36304985, 2022). "Interestingly, TRPV1 expression levels correlated negatively with the enrichment scores of the EMT signature in nine individual cancer types (p < 0.001)." (PMID 36304985, 2022). "Altered TRPV1 expression has been identified in numerous cancer cell types." (PMID 35402237, 2022). "This implies that in colon cancer, TRPV1 is probably activated by polyamines and may contribute to cancer pain." (PMID 36499622, 2022). "To determine if the lack of an intact immune system in athymic nude mice contributes to cancer-induced changes in TRPV1 expression, we measured TRPV1 expression in wildtype mice with 4NQO-induced oral SCC (oSCC, n = 4 female, 6 male) and vehicle treated mice (n = 4 female, 6 male)." (PMID 35260737, 2022). "However, overexpression of TRPV1 channels in the cancer cells made them more sensitive to capsaicin, indicating that TRPV1 expression level is associated with the magnitude of the response." (PMID 33804707, 2021). "In cancer chemotherapy, the TRPV1 agonist capsaicin has a synergic effect with cisplatin." (PMID 34131404, 2021). "However, TRPV1 either promotes or inhibits cell death, depending on cancer cell type, implying it has cancer- or tissue-specific functions." (PMID 34131404, 2021). "In addition, an apoptosis-inducing TRPV1 nanoagonist containing semiconducting polymer nanoparticles (SPNs) as nanocarriers and CPS as the agonist has been developed to target TRPV1-positive cancer cells." (PMID 34065398, 2021). "Whether TRPV1 regulates the secretion of inflammatory cytokines by cancer cells is not fully understood, and the mechanisms need to be further investigated." (PMID 34131404, 2021). "The transient receptor potential cation channel subfamily V member 1 (TRPV1) which is also known as the capsaicin receptor, is an overexpression protein in many cancers types whose function might be critical in various neuronal physiological conditions." (PMID 34836251, 2021).
cancer (continued). "TRPV1 and TRPA1 could be involved in the development of cancer-associated pain, mediated by the acidic tumor environment." (PMID 35053150, 2021). "That is why the TRPV1 channel offers new treatment possibilities for cancer." (PMID 34834237, 2021). "We further discuss the therapeutic potential of targeting TRPV1 in cancer cells." (PMID 34131404, 2021). "Nevertheless, the roles of TRPV1 antagonists in cancer therapy are controversial." (PMID 34131404, 2021). "Hence, more researchers are focusing on the effects of TRPV1 agonists or antagonists on cancer tumorigenesis and development." (PMID 34131404, 2021). "Given the fact that TRPV1 also plays several intracellular roles, it remains unclear whether TRPV1 functions independently of its channel activity in cancer progression." (PMID 34131404, 2021). "Overexpression of TRPV1 is reportedly involved in both tumor growth and cancer-induced pain." (PMID 36045706, 2021). "The evidence presented thus far supports the hypothesis that TRPV1 acts to suppress cancer cell proliferation." (PMID 34131404, 2021). "In this review, we will summarize the role of TRPV1 and TRPA1 in pain associated with cancer and discuss molecules that have been reported to modulate these channels, focusing particularly on the mechanisms of channel activation associated with molecules released in the tumor microenvironment." (PMID 35053150, 2021). "Similarly, melatonin supports the anti-cancer effects of the chemotherapeutic agent doxorubicin via TRPV1 activation and subsequent apoptosis in MCF-7 cells." (PMID 32545311, 2020). "However, our outcomes also showed certain discrepancies in TRPV1 expression and other cancer related genes." (PMID 32913462, 2020). "Finally, the enrichment of TRPV1 was inversely related to certain tumor promoting genes and positively correlated with several cancer inhibiting genes." (PMID 32913462, 2020). "Several researchers also focused on the tight relationship between TRPV1 and cancer." (PMID 32913462, 2020). "Several innovative anti-cancer strategies targeting TRPV1 are currently in development." (PMID 32545311, 2020). "TRPV1 channels also modulate the efficacy of existing anti-cancer therapies." (PMID 32545311, 2020). "TRPV1 has been shown to inhibit cancer cell proliferation by promoting apoptosis." (PMID 33187307, 2020). "Collectively, these results suggest a potential role for TRPV1 in human cancers." (PMID 32604833, 2020). "Ionic influx into the mitochondria is followed by apoptosis in TRPV1-positive cancer cells." (PMID 32545311, 2020). "In addition to their analgesic activity, transient receptor potential vanilloid 1 (TRPV1) agonists and antagonists demonstrate profound anti-cancer activities in various human cancers." (PMID 32604833, 2020). "TRPV1 has shown to be related to oncogenesis and is expressed in different types of cancer." (PMID 33178018, 2020). "Interestingly, recent studies have revealed that TRPV1 antagonists, as well as TRPV1 agonists, possess anti-cancer activities in various types of human cancer cells, in addition to their analgesic activity." (PMID 32604833, 2020). "Other previously documented cancer-induced pathways such as TRPV1 activation and extracellular acidity mean that pain in MM patients is likely to have a number of causative pathways, depending on the specific genetic makeup and cellular interactions of each MM case." (PMID 31578352, 2019). "This process involves an acidic area adjacent to the bone that results in upregulation of specific ion channels, such as transient receptor potential cation channel subfamily V member 1 (TrpV1), which results in cancer bone pain through sensitization and activation of nerve fibers." (PMID 31110519, 2019). "Therefore, TRPV1 provides a potential link between the process of inflammation, cancer and immunity, and offers new treatment possibilities." (PMID 31681615, 2019). "Effects of the capsaicin and TRPV1 blockade on the cancer cells." (PMID 31681615, 2019).
cancer (continued). "Similarly, Glial cell line–Derived Neurotropic Factor (GDNF) and artemin (ARTN), released by cancer, increase TRPV1 expression and thus pain sensibility." (PMID 31248001, 2019). "As a result, the enhanced anti-cancer effect was diminished by the TRPV1 blocker." (PMID 29338036, 2018). "The pro-apoptotic activity of capsaicin is mediated through TRPV1 in many cancers." (PMID 30347711, 2018). "Chinese medicine such as Fufang Kushen injection could reduce cancer pain directly by blocking TRPV1 signaling pathway." (PMID 30254688, 2018). "Wakabayashi showed that the disruption of the TRPV1 gene attenuated cancer-induced bone pain." (PMID 30366393, 2018). "Establishing the relationship between TRPV1 expression levels, and characteristics such as the tumor grade (predicted aggressiveness of the tumor) or tumor stage (tumor size and degree of spread), aids in determining its potential role in cancer." (PMID 29066974, 2017). "The trial also will provide evidence on better end-of-life quality and palliative care of cancer patients and deliver the proof of concept of molecular neurosurgery: only TRPV1+ acheurons, a verified subset of sensory neurons, can be removed by RTX-induced cytotoxicity." (PMID 28626428, 2017). "There is an increase in TRPV1 expression in the DRG of animals with cancer-induced bone pain, and pharmacological blockade of TRPV1 attenuates cancer-induced bone pain, suggesting that TRPV1 activation plays a critical role in the generation of at least some types of bone pain." (PMID 28955292, 2017). "Furthermore, TRPV1 was shown as a regulator of growth factor signaling in the suppression of tumorigenesis, and its anti-cancer effect was also confirmed." (PMID 27120617, 2016). "Thus, we showed that the use of the membrane receptor blockers Capsazepine or AMG-9810, TRPV1 antagonists, and TRPV1 siRNA resulted in decreased heat shock proteins, Hsp70 and Hsp90 in cancer cells." (PMID 27200359, 2016). "A number of studies have shown that TRPV1 plays an integral role in cancer pain." (PMID 27854251, 2016). "TRPV1 antagonism reduces cancer-induced thermal hyperalgesia in these models." (PMID 24524628, 2014). "In contrast, in other reports, activation of TRPV1 leads to induction of apoptosis in cancer cells." (PMID 24381558, 2013). "However, capsaicin was shown to have TRPV1-independent effects, such as inhibition of voltage-gated calcium channels, cancer cell growth inhibition and apoptosis induction." (PMID 24106480, 2013). "In this regard, TRPV1 activation sensitized cancer cells to TNFR-mediated apoptosis." (PMID 22523714, 2012). "Recent studies have revealed that TRPV1 is involved in the development of cancer-induced pain." (PMID 21118579, 2010). "This implies that under an acidic microenvironment of cancer tissues, TRPV1 may play a more critical role than TRPA1." (PMID 20422007, 2010). "Consequently, over-expression of TRPV1 increases mechanical sensitization by decreasing pain thresholds of patients with cancer." (PMID 20422007, 2010). "TRPV1 has been shown to be up-regulated by TNFα in cancer-related thermal hyperalgesia in mice." (PMID 19753113, 2009). "Our study suggests that TRPV1 may be able to regulate the tumor microenvironment by regulating immune-related physiological activities and thereby regulating the occurrence and progression of cancers." (PMID 41535811, 2026). "Therefore, the expression level of TRPV1 can be used for the diagnosis and prognosis of cancer." (PMID 40007993, 2025). "The higher expression of TRPV1 in more malignant cancer cell lines may be due to the fact that it mainly promotes cell proliferation; On the contrary, the lower expression of TRPV1 in the more malignant cancer cell lines may be due to the fact that it mainly plays a role in promoting apoptosis." (PMID 40007993, 2025).
cancer (continued). "Additionally, TRPV1, a calcium‐permeable ion channel, was shown to become desensitized with cannabinoid treatment, leading to calcium dysregulation, endoplasmic reticulum (ER) stress, and cancer cell death." (PMID 40781861, 2025). "The activation of TRPV1 affects apoptosis or proliferation through different and competitive pathways, which may explain why TRPV1 is differently expressed in different types of cancer and the reason and effect of the expression change." (PMID 40007993, 2025). "Besides, TRPV1 has also been reported to be involved in the process of cancer." (PMID 40013655, 2025). "Therefore, Ca2+ influx into the cytoplasm after activation of TRPV1 will change the balance between apoptosis and proliferation signaling pathways, which may promote the development of cancer and may also have anti-tumor effects." (PMID 40007993, 2025). "However, large gaps remain in our knowledge since the mechanisms by which cancer activates TRPV1 are essentially unknown." (PMID 38339399, 2024). "Similar, the mitochondrial TRPV1-mediated “death mechanism” may also operate in cancer cells." (PMID 37240443, 2023). "Although it will be important in future studies to assess the precise underlying mechanisms by which TRPV1 regulates autophagy-dependent EGFR activation, this connection immediately hints at several potentially promising therapeutic targets to control cisplatin-resistant cancer in the clinic." (PMID 37165076, 2023). "We believe that TRPV1 blockade represents as an effective approach to dismantle self-defenses in tumors for amplifying thermo-immunotherapy against a variety of highly malignant tumors, and offer an insightful avenue in the ion channel blockade toward potent cancer therapy." (PMID 37120615, 2023). "Thus, we provide proof-of-concept evidence that TRPV1 inhibition could be a clinically available strategy to control NANOGhigh cisplatin-resistant cancer and CIPN." (PMID 37165076, 2023). "Taken together, it is suggested that blocking the activation of the SN TRPV1 has anti-cancer and analgesic effects in the acidic bone microenvironment associated with BC colonization, Thus, SN TRPV1 may play as a mediator of biological interactions between BCIBP and BC progression in bone." (PMID 37461623, 2023). "Thus, targeting TRPV1 in chemotherapy-resistant cancer could be an actionable strategy in overcoming MDR." (PMID 37165076, 2023). "Thus, we provide proof-of-concept evidence that TRPV1 inhibition could be a plausible strategy to control NANOGhigh cisplatin-resistant cancer as well as CIPN." (PMID 37165076, 2023). "For instance, TRPV1 activation may actually accelerate cancer growth." (PMID 37371563, 2023). "In immune cells and cancer, subcellular TRPV1 may be involved in as-yet unsuspected functions." (PMID 37371563, 2023). "However, topically administered TRPA1 and/or TRPV1 agonists could avoid systemic unwanted effects, and therefore, might provide beneficial treatment potentials on the oral mucosa even against cancer generation and progression." (PMID 35163843, 2022). "Notably, the influence of TRPV1 on the PI3K/Akt signaling pathway may hold implications for the circumvention or minimization of cancer drug resistance." (PMID 32545311, 2020). "Interestingly, TRPV1 antagonists such as capsazepine also induced cell death in several cancers." (PMID 32604833, 2020). "However, the cytotoxic activity of DWP05195 was not strongly associated with the levels of TRPV1 in the cancer cells." (PMID 32604833, 2020).
cancer (continued). "Our clinicopathologic study suggested that TRPV1 might be a human GC suppressor, and therefore its inhibition on GC cell proliferation was tested since high proliferation is a major characteristic of cancer cells." (PMID 33008449, 2020). "Interestingly, the TRPV1 expression is inversely correlated with the grade in GBM, suggesting that TRPV1 may negatively control cancer progression." (PMID 31801263, 2019). "Also, little is known about functional expression of TRPV1 in cancer cells." (PMID 31681615, 2019). "In order to realize whether TRPV1 is involved in the synergistic anti-cancer effect, the selective TRPV1 antagonist SB-705498 ((N-(2-bromophenyl)-N’-[((R)-1-(5-tri-fluromethyl-2-pyridyl)pyrrolidin-3-yl)]urea) was incubated with the cells 30 min before SMF and capsaicin treatments." (PMID 29338036, 2018). "In many reports to date, the action of agonists on TRPV1 has been found to inhibit cell migration; therefore, capsaicin and related TRPV1 agonists are considered to have the potential to inhibit cancer progression, leading to anticipation that they may be effective as antitumor drugs." (PMID 28081185, 2017). "Hence, lipid therapy and antagonists of membrane-bound receptors, such as TRPV1, could allow us to modulate the heat sensing route of cancer cells, hence curtailing their pro-survival mechanisms." (PMID 27200359, 2016). "In addition, TRPA1 is co-expressed with TRPV1, is also activated by oxidized lipids, modulates the activity of TRPV1 and may participate in cancer pain." (PMID 26007300, 2015). "Indeed, TRPV1 expression is upregulated in neurons of mouse and rat models of cancer." (PMID 24524628, 2014). "Therefore, we hypothesize that the proliferating cancer cells secrete excessive endogenous formaldehyde in the initial stages, and then formaldehyde up-regulates TRPV1 expression in the afferent nerves." (PMID 20422007, 2010). "Corydalis alkaloids, aconitine derivatives, and curcumin all exhibit activity on TRPV1 and TRPA1 channels, which are critical mediators of thermal and mechanical hyperalgesia in cancer pain." (PMID 41531828, 2026). "Thus, TRPV1 could be used to develop new-targeted drugs for cancers." (PMID 41535811, 2026). "Our data shed light on the molecular mechanisms regulating TRPV1 activity during pain resolution, suggesting that targeting TRPV1 palmitoylation could mitigate clinically intractable chronic pain, such as neuropathic pain, cancer-related pain, and various forms of chronic inflammatory pain." (PMID 39528731, 2025). "Therefore, TRPV1 may play a multi-directional role in cancer tissue." (PMID 40007993, 2025). "Intraperitoneal administration of quetiapine improved the paw withdrawal pressure threshold, as a sign of reduced nociception, and was correlated with lower mRNA levels of TRPV1 and TRPV4 in C3H/HeN mice with cancer pain." (PMID 39940997, 2025). "Recent studies suggest that the main channels involved in the oxidative stress-mediated cancer process are TRPML1, TRPA1, TRPM2 and TRPV1." (PMID 40813985, 2025). "This body of research underscores the critical role of TRPV1 and TRPV6 in mediating capsaicin-induced apoptosis across different cancer cell types through calcium-dependent mechanisms." (PMID 39407657, 2024). "TRPV1-expressing nerve endings release calcitonin gene-related peptide (CGRP) that, in turn, can stimulate cancer growth." (PMID 38339399, 2024). "Similarly, TRPV1 expression on dendritic cells could modulate immune responses, affecting tumor growth and metastasis, highlighting its potential in developing immunotherapeutic strategies for cancer." (PMID 39407657, 2024). "In a murine model of cancer pain, intrathecal RTX produced lasting analgesia, similar to that observed after disruption of the Trpv1 gene." (PMID 37894723, 2023). "As both Trpv1 and Trpv4 were expressed by MNTs, and responsive to pain inducer capsaicin, their roles in the MNT-mediated cancer pain are worth further elucidation for developing novel analgesics." (PMID 36206343, 2022).